RSU1P2 (Ras suppressor protein 1 pseudogene 2)
Gene: Transcribed unprocessed pseudogene on chromosome 10 (45,106,610 to 45,116,101, reverse strand). Ensembl gene ENSG00000232554.
Diseases named in the same sentence as RSU1P2 in open-access papers:
RSU1P2 is named in the same sentence as 7 diseases in open-access papers, as found by Europe PMC text mining. Sharing a sentence is not in itself a finding about the gene and the disease. The quoted sentences say what the papers report.
cervical cancer (11 papers, 2017 to 2026). A primary or metastatic malignant neoplasm involving the cervix. "In cervical cancer, high expression of the lncRNA Ras suppressor protein 1 pseudogene 2 (RSU1P2) was associated with VM formation." (PMID 31993365, 2019). "To determine whether alterations in the EMT is responsible for the promotion of invasion and migration caused by RSU1P2 in cervical carcinoma cells, we performed western blot assays to detect the protein levels of the epithelial marker E-cadherin and the mesenchymal markers vimentin and ICAM-1." (PMID 27487126, 2017). "For example, a previous study has suggested that the lncRNA Ras suppressor protein 1 pseudogene 2 (RSU1P2) mediates gene expression in cervical cancer by functioning as a ceRNA of let-7a." (PMID 33836753, 2021). "Collectively, these observations provide strong evidence that RSU1P2 promotes tumorigenesis in cervical cancer." (PMID 27487126, 2017). "For example, the lncRNA Ras suppressor protein 1 pseudogene 2 (RSU1P2) was shown to be overexpressed in cervical cancer and to play a tumor-promoting role by acting as a ceRNA for microRNA let-7a and regulating the expression of IGF1R, N-myc, and EphA4." (PMID 28209205, 2017). "To investigate the role of RSU1P2 in cervical cancer, we first measured the expression levels of RSU1P2 in 14 pairs of human cervical cancer tissues and adjacent normal tissues using qRT-PCR." (PMID 27487126, 2017). "We have revealed that RSU1P2 promotes the malignancy of cervical cancer and is downregulated by let-7a." (PMID 27487126, 2017). "Here, we found that the lncRNA Ras suppressor protein 1 pseudogene 2 (RSU1P2) is upregulateded in cervical cancer tissues and has a tumour-promoting role." (PMID 27487126, 2017). "We also examine the expression level of RSU1P2 in three kinds of cervical cancer cells, Caski, HeLa and C33A, RSU1P2 levels were higher relative to that in Caski cells." (PMID 27487126, 2017). "We therefore provide evidence that aberrant regulation of RSU1P2 via miRNA competition by ceRNAs contributes to cervical carcinoma development." (PMID 27487126, 2017). "Collectively, these observations strongly suggest that RSU1P2 promotes the G1/S transition in cervical carcinoma cells." (PMID 27487126, 2017). "For instance, RSU1P2 boosted the cervical cancer growth via serving as a ceRNA against let-7a." (PMID 34419049, 2021). "Additionally, to explore the mechanism of RSU1P2 in promoting cell growth and proliferation, we investigated the effects of RSU1P2 on the cell cycle and on apoptosis in cervical cancer cells." (PMID 27487126, 2017). "To illustrate the mechanism of RSU1P2 upregulation in cervical cancer, we predicted the RSU1P2 promoter by bioinformatics and cloned a 2947-bp fragment upstream from the known RSU1P2 5′ end into pGL3-basic vector (pGL3-basic/ RSU1P2-p2937, RSU1P2-p2937)." (PMID 27487126, 2017). "In addition, the pseudogene-expressed lncRNA RSU1P2 was found to be significantly up-regulated in cervical cancer, and functioned as an oncogene in cervical cancer cells." (PMID 28779166, 2017). "To examine whether the ceRNA activity of RSU1P2 in cervical carcinoma cell lines is relevant to the human disease, we measured let-7a and the RNA levels of its targets in patients samples." (PMID 27487126, 2017). "Understanding the effect of RSU1P2 on the cellular malignancy will help elucidate the pathogenesis of aggressive cervical carcinoma and provide a basis for novel targeted therapies for cervical carcinoma treatment." (PMID 27487126, 2017). "First, RSU1P2 is overexpressed in cervical carcinoma tissues and could enhance proliferation, angiogenesis, invasion and migration capacity, promote EMT and the G1/S transformation of HeLa and C33A cells, thus functioning as an oncogene." (PMID 27487126, 2017).
cervical cancer (continued). "Furthermore, we revealed that the binding of RSU1P2 to the let-7a miRNA relieved the suppression of the let-7a-targeted genes IGF1R, N-myc and EphA4, which may explain role of RSU1P2 in tumorigenesis of cervical cancer." (PMID 27487126, 2017). "Importantly, this observed interaction extended beyond in vitro cell line data to human clinical samples: let-7a levels were decreased in cervical carcinoma tissue samples compared with corresponding adjacent normal tissue, consistent with upregulated RSU1P2 expression." (PMID 27487126, 2017). "qRT-PCR analysis indicated that let-7a expression was downregulated, but RSU1P2 expression was upregulated, in cervical cancer tissues compared with adjacent non-tumor tissues." (PMID 27487126, 2017). "To explore its role in carcinogenesis, we first demonstrated that RSU1P2 was upregulated in cervical cancer tissues compared with adjacent non-tumor tissues and functionied as an oncogene in cervical cancer cells." (PMID 27487126, 2017). "The results showed that RSU1P2 expression levels were markedly increased in cervical cancer tissues compared with matched non-tumor tissues, which prompted us to speculate that RSU1P2 expression may correlate with the malignant behaviors of cervical carcinoma." (PMID 27487126, 2017).
liver cancer (2 papers, 2022 to 2026). An epithelial or non-epithelial malignant neoplasm that arises from the liver. "The RSU1P2/let-7a/Tex10 axis is involved in the development of liver cancer and can be an interesting target due to its regulatory function in the expression of CSC-related genes, as well as in processes like apoptosis and epithelial-to-mesenchymal transition." (PMID 41431719, 2026). "LncRNA RSU1P2 functions as a cancer-promoting gene in liver cancer and promotes tumorigenesis in vivo." (PMID 35156514, 2022). "We therefore considered that LncRNA RSU1P2 acted as an oncogene in liver cancer by negatively regulating let-7a." (PMID 35156514, 2022). "In this study, RSU1P2 expression was elevated whereas let-7a was remarkably restrained in liver cancer tissues and cells, and let-7a level was negatively related with RSU1P2 expression in liver cancer tissues." (PMID 35156514, 2022). "This study assumes that LncRNA RSU1P2 is elevated in liver cancer tissues and cells, and acts as a cancer-promoting gene in liver cancer." (PMID 35156514, 2022). "In this study, the expression of LncRNA RSU1P2 was significantly elevated in liver cancer tissues and cells." (PMID 35156514, 2022). "In this study, LncRNA RSU1P2 was raised in cancer tissues from liver cancer patients and liver cancer cell lines." (PMID 35156514, 2022). "The oncogenic roles of RSU1P2 in liver cancer were observed in the in vivo experiment." (PMID 41431719, 2026). "RSU1P2 positively regulates Tex10 mRNA expression by targeting let-7a in liver cancer." (PMID 41431719, 2026). "Therefore, we assumed that LncRNA RSU1P2 acted as an oncogene in liver cancer by promoting Tex10 via sponging let-7a." (PMID 35156514, 2022). "Therefore, LncRNA RSU1P2 promotes tumorigenesis and cancer stem cell-like properties in liver cancer through let-7a/Tex10 pathway." (PMID 35156514, 2022). "Besides, LncRNA RSU1P2 facilitates liver cancer cells proliferation, invasion, EMT, and cancer stem cell-like properties through let-7a/Tex10 pathway in vitro." (PMID 35156514, 2022). "We verified that LncRNA RSU1P2/let-7a/Tex10 pathway promoted liver cancer cell proliferation, invasion, EMT and the expression of cancer stem cell-related genes in vitro and confirmed our hypothesis in vivo." (PMID 35156514, 2022). "Thus, we first revealed that LncRNA RSU1P2 was elevated in liver cancer, which suggested that the up-regulation of LncRNA RSU1P2 might exert important function in the progression of liver cancer." (PMID 35156514, 2022). "Thus, we have revealed the role of LncRNA RSU1P2/let-7a/Tex10 pathway in controlling tumorigenesis and cancer stem cell-like properties in liver cancer, which may supply potential therapeutic targets for liver cancer treatment." (PMID 35156514, 2022). "In this study, Tex10 restoration abolished the inhibition effect of RSU1P2+ let-7a on cell viability, proliferation, invasion, EMT of liver cancer cells, and the expressions of cancer stem cell-related genes." (PMID 35156514, 2022). "Besides, knockdown of RSU1P2 repressed cell viability, invasion, epithelial-mesenchymal transition (EMT) of liver cancer cells and the expressions of cancer stem cell-related genes, whereas facilitated the apoptosis of liver cancer cells." (PMID 35156514, 2022). "However, the role of LncRNA Ras suppressor protein 1 pseudogene 2 (RSU1P2) in modulating tumorigenesis and cancer stem cell-like properties in liver cancer is still not known." (PMID 35156514, 2022).
bladder cancer (1 paper, 2017). "In addition, TCGA data showed that RSU1P2 is high-expression in breast cancer, bladder cancer and prostate cancer, it needs to be unraveled whether that RSU1P2 exerts the similar role in these cancer cells." (PMID 27487126, 2017).
tumor (4 papers, 2017 to 2024). "Furthermore, vasculogenic mimicry (VM) analysis showed support for the tumor-promoting role of RSU1P2." (PMID 27487126, 2017). "To further examine the effect of RSU1P2 on tumor growth in vitro, we obtained HeLa pooled clones (HeLa/ RSU1P2-full) that stably expressed higher levels of RSU1P2 and HeLa/pcDNA3 pooled clones by G418 screening and injected the cells into the flanks of 7 nude mice." (PMID 27487126, 2017). "According to the known tumor suppressive function of let-7a, we speculated that upregulated RSU1P2 sequesters let-7a to inhibit its tumor-suppressive effects." (PMID 27487126, 2017). "Finally, RSU1P2 knockdown suppressed tumor volume, tumor weight, and EMT in a xenograft model." (PMID 35156514, 2022). "Bioinformatics analysis revealed that the RSU1P2 transcript contains many potential binding sites for various miRNAs, including the tumor suppressive let-7 family, miR-122 and miR-143, which are downregulated in numerous types of cancer, suggesting that RSU1P2 may act as a ceRNA." (PMID 27487126, 2017).
cancer (2 papers, 2017 to 2022). A tumor composed of atypical neoplastic, often pleomorphic cells that invade other tissues. "Hence, cancer-selective targeting of RSU1P2 could have strong benefits." (PMID 27487126, 2017).
RSU1P2 also shares sentences with these, for which no sentence is quoted: breast carcinoma (1 paper); prostate carcinoma (1).